PTPN13 (protein tyrosine phosphatase non-receptor type 13)
Diseases named in the same sentence as PTPN13 in open-access papers (continued):
Sharing a sentence is not in itself a finding about the gene and the disease.
myeloid leukemia (2 papers, 2012 to 2018). A clonal proliferation of myeloid cells and their precursors in the bone marrow, peripheral blood, and spleen. "We determined that transcription of the PTPN13 promoter (encoding Fap1) was repressed by Icsbp/Irf8 (interferon consensus sequence binding protein/interferon regulatory factor 8) in myeloid leukemia cells." (PMID 29899829, 2018). "Based on observations in myeloid leukemia, IRF-8 may regulate Fas responsiveness by acting as a transcriptional activator of pro-apoptotic genes, such as caspases, and/or a transcriptional repressor of anti-apoptotic genes, such as PTPN13 (FAP-1) or members of the Bcl-2 family." (PMID 23028998, 2012).
serous ovarian carcinoma (2 papers, 2017 to 2020). "Finally, to strengthen these results, we assessed survival and tumor PTPN13 expression in a larger HGSOC dataset using the TCGA metadata on serous ovarian cancer samples (Grade 3) and the on-line Km-plotter tool." (PMID 29221157, 2017).
squamous cell lung carcinoma (2 papers, 2013 to 2020). A carcinoma arising from squamous bronchial epithelial cells. "Here, we demonstrate that PTPN13 is a direct transcriptional target of Stat3 in the squamous cell lung carcinoma." (PMID 24191246, 2013).
acute lymphoblastic leukaemia (1 paper, 2024). "Thus, PTPN13 may suppress oncogenic Src signalling, whilst the loss of PTPN13 expression or germ-line mutations in PTPN13 have been described in NSCLC and acute lymphoblastic leukaemia, respectively." (PMID 38334623, 2024).
acute T cell leukaemia (1 paper, 2012). "For example, the CADM1 partners, TIAM in acute T cell leukaemia or PTPN13 in epithelial cells, are not expressed in MCs." (PMID 22438059, 2012).
bladder carcinoma (1 paper, 2020). "Conversely, FAS surface expression is upregulated after transfection of TIG3 bladder carcinoma cells with PTPN13 dominant negative mutants or after PTPN13 silencing by siRNA." (PMID 33322542, 2020).
concussion (1 paper, 2017). A concussion, also known as a mild traumatic brain injury (mTBI), is a head injury that temporarily affects brain functioning. "We postulate that calpain-2 activation following TBI (and possibly concussion) could lead to PTPN13 truncation, resulting in increased phosphorylation of c-Abl and its activation." (PMID 28924170, 2017).
endometrioid carcinoma (1 paper, 2017). "This is important, because by analyzing PTPN13 RNA expression in 12 endometrioid carcinoma samples, which have a better prognosis than HGSOC, we observed a heterogeneous expression with a slightly lower mean expression level than in HGSOC (data not shown)." (PMID 29221157, 2017).
esophageal cancer (1 paper, 2012). A primary or metastatic malignant neoplasm involving the esophagus. "This expression pattern is similar to that of PTPN7 and PTPN13, which were reported to be at a global loss in a wide range of cancers including breast, kidney, and esophageal cancers." (PMID 22394684, 2012).
gastric cancer (1 paper, 2020). A primary or metastatic malignant neoplasm involving the stomach. "Around 6% of TCGA gastric cancer samples harbor PTPN13 mutations that have been associated with poor prognosis." (PMID 33322542, 2020).
liver cancer (1 paper, 2021). An epithelial or non-epithelial malignant neoplasm that arises from the liver. "An analysis of three independent cohorts, which included a 179-patient Stanford University cohort (GSE3500), a 45-patient Mount Sinai Liver Cancer Program cohort (GSE6764), and a 445-patient National Cancer Institute cohort (GSE14520), proved that PTPN13 expression was downregulated in HCC tissue." (PMID 33051595, 2021).
myeloid malignancies (1 paper, 2022). "Transcription levels of PTPN13 are abnormally elevated in myeloid malignancies." (PMID 36699453, 2022).
neurofibromatosis type 1 (1 paper, 2022). A clinically heterogeneous, neurocutaneous genetic disorder characterized by cafe-au-lait spots, iris Lisch nodules, axillary and inguinal freckling, and multiple neurofibromas. "Genes co-expressed with PTPN13 were correlated with “Immune response_HMGB1 release from the cell”, “Putative pathways of hormone action in neurofibromatosis type 1”, and “Immune response_HMGB1/RAGE signaling pathway”." (PMID 36556168, 2022).
pancreatic ductal adenocarcinoma (1 paper, 2022). An infiltrating adenocarcinoma that arises from the epithelial cells of the pancreas. "The expression of PTPN13 was also higher in pancreatic ductal adenocarcinoma with a fold change of 2.100 in Badea dataset versus normal samples." (PMID 35154122, 2022).
Rett syndrome (1 paper, 2021). A severe neurodevelopmental disorder affecting the central nervous system. "While PTPN13 has been shown to play a role in T cell activation, it is specifically expressed in Th17 T cells and has variable expression in T cells of people with Rett Syndrome." (PMID 34252097, 2021).
tumor (68 papers, 2004 to 2026). "The terminal valine of APC11 plays a key role in binding to PTPN13, as mutation of this residue to alanine significantly reduces the binding affinity and anti-tumor efficacy of the peptide." (PMID 41486293, 2026). "Among these, PTPN13, a known tumor suppressor, showed a strong association with ALV-J susceptibility." (PMID 40427243, 2025). "PTPL1 is a protein tyrosine phosphate (PTP) encoded by the human PTPN13 gene, which can exert tumor suppressor role by antagonizing protein tyrosine kinase (PTK)." (PMID 38766487, 2024). "Mutations of PTPN13 or ERBB2 in the primary tumor were correlated with significantly shorter PFS (P = 0.014 and 0.0034, respectively)." (PMID 37131253, 2023). "PTPN13 expression is frequently downregulated or silenced through promoter hypermethylation or loss of heterozygosity in several tumor types 18-20." (PMID 31938048, 2020). "The confirmation of the prognostic value of PTPN13 justifies determining its role in tumor progression and the underlying mechanisms." (PMID 31938048, 2020). "For example, disruptive PTPN13 mutations have been found in various tumor samples including HPV-negative head and neck squamous cell carcinomas." (PMID 29439552, 2018). "The nonsense mutation (Tyr1758∗∗∗) in PTPN13 leads to loss of function in accord with the prior study reasoning PTPN13 as a candidate tumour suppressor gene in HCC." (PMID 29333154, 2017). "In both cohorts, high PTPN13 expression level (mRNA or protein) in the tumor was associated with favorable outcome and significantly longer survival (HR=0.27; p=0.0087 and HR=0.42; p=0.03, respectively)." (PMID 29221157, 2017). "PTPN13 (NP_542416.1, ~2490 aa), is a multi-module containing phosphatase, with mediate associations with many cellular proteins in several steps of tumor progression." (PMID 27285768, 2016). "Using ccRCC and matched normal kidney samples, it was also evidenced that the increased levels of miR-185 and miR-21 in tumors correlate with the loss of function of specific tumor suppressors such as PTPN13, SLC12A1 and TCF21." (PMID 26670229, 2015). "We next investigated the role of PTPN13 in APC-loss-induced tumor immune evasion." (PMID 41486293, 2026). "Moreover, decreased PTPN13 expression synergizes with an activated ErbB2 transmembrane mutation (mNeuNT), which further enhances tumor progression and invasion in vivo." (PMID 24191246, 2013). "Moreover, we previously found that decreased PTPN13 expression synergizes with an activated ErbB2 transmembrane mutation (mNeuNT) enhancing tumor growth and invasion in vivo." (PMID 22279592, 2012). "In addition, we developed a conditional Ptpn13 knockout mouse model (Ptpn13fl/fl), which we crossed with Villin-CreERT2 mice and ApcMin/+ mice (spontaneous tumor mouse model carrying a single mutant Apc allele) to generate ApcMin/+/Ptpn13fl/fl/Vil-CreERT2 (APV) mice." (PMID 41486293, 2026). "Notably, sgRNAs targeting Ptpn13 were significantly depleted in tumors from WT Balb/c mice compared with those from nude mice, indicating that loss of PTPN13 impairs tumor growth specifically in an immune-competent context and suggesting its critical role in facilitating immune evasion." (PMID 41486293, 2026). "The identification of a previously unrecognized APC/PTPN13/STAT1-dependent tumor immune-suppressive mechanism in this study represents a significant advance, offering a compelling strategy for development of therapeutic interventions for CRC." (PMID 41486293, 2026). "The role of PTPN13 in cancer has been controversial, with evidence suggesting both tumor-promoting and tumor-suppressive functions, depending on the context." (PMID 41486293, 2026). "To further investigate the immune-dependent effects of PTPN13 depletion, we performed a competitive tumor growth assay." (PMID 41486293, 2026).
tumor (continued). "Immunohistological analysis of the CT26-shApc tumors from Balb/c mice showed that Ptpn13 knockout in tumor cells significantly increased CD8+ T cell infiltration without affecting tumor cell proliferation." (PMID 41486293, 2026). "In the MC38-Ova tumor model, Ptpn13 knockout enhanced OVA antigen presentation on MC38-Ova-shApc cells and increased the frequency of antigen-specific CD8+ T cells, indicating improved antigen-specific CD8+ T cell responses." (PMID 41486293, 2026). "We generated a mouse model in which an HA tag was fused to the C terminus of APC, thereby disrupting the interaction with PTPN13, and this also resulted in increased tumor burden and reduced immune activity." (PMID 41486293, 2026). "By contrast, in WT Balb/c mice, CT26-Ptpn13-sgRNA cells (GFP+) were significantly depleted, demonstrating that PTPN13 loss sensitizes tumor cells to immune-mediated elimination." (PMID 41486293, 2026). "PTPN13, a tumor suppressor and localizing to specific sites along the mitotic spindle, regulates cellular proliferation and invasive characteristics in multiple epithelial cells in tumors through accommodating cell circle." (PMID 41573567, 2025). "Meanwhile, SHROOM4 was found to co-express with PTPN13/CACNA1C impacting the tumor microenvironment (TME) and to participate in critical signaling pathways like cell circle and WNT." (PMID 41573567, 2025). "Low expression of SHROOM4 reduces the tumor-suppressive effect of PTPN13, leading to uncontrolled cell cycle progression in LUAD." (PMID 41573567, 2025). "In humans, PTPN13 is discussed as a potential tumour suppressor that regulates cell growth in various tissues, resulting in better outcomes for those affected." (PMID 39300329, 2024). "This inhibitory effect of PTPN13 on cell migration and invasion is consistent with the observations in other tumor types." (PMID 37895093, 2023). "PTPN13’s role in the responsiveness to cancer therapies appears to be highly dependent on the tumor type." (PMID 37895093, 2023). "PTPN13 expression is a prognostic marker in many tumor types, including HGSOC, but its mechanism of action in HGSOC had not been studied." (PMID 37895093, 2023). "In our report, the results showed that PTPN13 expression in normal tissues is lower than that in PAAD tissues, but PTPN13 expression in PAAD patients has nothing related to the tumor stage." (PMID 35154122, 2022). "Our results suggest that decreased expression of miR-200b, ZEB2 and PTPN13 is involved in local tumour spread of CRC, particularly in serosal invasion (pT4a)." (PMID 36140249, 2022). "Nevertheless, a small number of PTPN family members exert more specific functions, for instance, PTPN11 as a tumor promoter whereas PTPN13 as a tumor suppressor in almost all cancers." (PMID 35957898, 2022). "From this list, we chose to focus on PTPN13 because it has been previously shown to have tumor-suppressive functions." (PMID 34265306, 2021). "We found that PTPN13 expression was significantly downregulated in tumor tissue samples compared with normal adjacent tissue samples in the TCGA database and negatively correlated with tumor stage." (PMID 33051595, 2021). "Low PTPN13 expression was significantly associated with HBV positivity, a tumor size ≥5 cm, ≥2 tumors, and venous invasion, as determined by clinicopathological analysis." (PMID 33051595, 2021). "PTPN13 is a member of the protein tyrosine phosphatase family and has previously been shown to have tumor-suppressive functions." (PMID 34265306, 2021). "Altogether, these results establish PTPN13 inhibitory role in cell migration and invasion in numerous tumor cell models." (PMID 31938048, 2020).
tumor (continued). "By transfecting wild-type and PBM-mutated E6 proteins in human and mouse keratinocytes, Spanos’ group confirmed that HPV16-induced degradation of PTPN13 promotes anchorage-independent tumor cell proliferation." (PMID 33322542, 2020). "In solid tumors, PTPN13 tumor suppressor role, via inhibition of pathways involved in cell proliferation and migration, seems to be confirmed by clinical studies." (PMID 33322542, 2020). "Taken together, our findings strengthen the interest to unravel the signaling pathways regulated by PTPN13 to identify new therapeutic targets involved in cell tumor invasion and metastasis formation." (PMID 31938048, 2020). "Altogether these results demonstrate that PTPN13 can inhibit tumor development and growth through its phosphatase activity." (PMID 31938048, 2020). "We focus particularly on its role in cancer, where PTPN13 acts as an oncogenic protein and also a tumor suppressor." (PMID 33322542, 2020). "This RAS effect is not observed when cells are co-transfected with PTPN13 shRNA or PBM-mutated E6, suggesting that RAS activation acts in conjunction with PTPN13 inhibition to promote tumor proliferation." (PMID 33322542, 2020). "Specifically, in athymic mice, PTPN13 knock-down promoted tumor growth and invasiveness and reduced cell adhesion." (PMID 31938048, 2020). "By using a siRNA against PTPN13 in combination with an inhibitor of IκBα phosphorylation or an IκBα mutant (Y42A), they confirmed that PTPN13 exerts its tumor suppressive effect by dephosphorylating IκBα at Tyr42." (PMID 33322542, 2020). "Accumulating evidences suggested that PTPN13 acts as a tumor suppressor in human cancers such as colorectal cancer, and breast cancer." (PMID 29558404, 2018). "PTPN13 is an enigmatic player in the cancer field, displaying both oncogenic as well as tumor suppressive functions depending on tumor context." (PMID 29439552, 2018). "The median PFS time was 1.3 years (95% CI [0.87 – 2.85]) in the low PTPN13 group (tumor PTPN13 expression lower than the median IRS which is 8), and 2.7 years (95% CI [0.85 – not reached]) in the high PTPN13 group (tumor PTPN13 expression ≥ 8)." (PMID 29221157, 2017). "This analysis showed a significantly longer survival for patients with high tumor PTPN13 expression." (PMID 29221157, 2017). "We previously demonstrated that nectin-like molecule-2 (Necl-2)/cell adhesion molecule 1 cis-interacts with ErbB3 via the extracellular region and with the protein tyrosine phosphatase PTPN13, a tumour suppressor, via the cytoplasmic region." (PMID 28900130, 2017). "Then, patients were divided in two groups according to the median tumor PTPN13 mRNA expression level (≤1.55: low PTPN13 group; >1.55: high PTPN13 group)." (PMID 29221157, 2017). "PTPN13 as tumour suppressor gene induced cell apoptosis via inhibition of the IRS‐1/PI3K/Akt signalling pathway." (PMID 28653805, 2017). "Other groups confirmed PTPN13 tumor suppressor gene properties and its role in tumor sensitivity to tyrosine kinase inhibitors." (PMID 29221157, 2017). "In multivariate analyses, a trend for a better survival was observed in patients with high tumor PTPN13 expression (HR=0.46; P=0.058)." (PMID 29221157, 2017). "Univariate Cox regression analysis showed that PFS and OS were significantly longer in patients with high tumor PTPN13 mRNA expression (HR=0.32, p=0.0101; and HR=0.27, p=0.0087, respectively)." (PMID 29221157, 2017). "We found that in HGSOC, PTPN13 protein expression is heterogeneous and is reduced in one third of tumor samples compared with normal ovary epithelium." (PMID 29221157, 2017). "The expression level of PTPN13 increased significantly in the tumor samples treated with miR-26a inhibitors by IHC study." (PMID 27285768, 2016). "For example, the protein tyrosine phosphatase PTPN13 has been proposed to function as a tumor suppressor; this is in line with its downregulation." (PMID 23371019, 2013).